TNF (tumor necrosis factor)
Diseases named in the same sentence as TNF in open-access papers (continued):
Sharing a sentence is not in itself a finding about the gene and the disease.
colorectal cancer (continued). "In this study, we found the upregulation of miR-105 in colorectal cancer was associated with aggressive phenotype, and the enhanced expression of miR-105 was required for TNF-α-induced epithelial–mesenchymal transition (EMT)." (PMID 29238068, 2017). "The variant is also highly correlated (R2=0.91) with an exonic variant in SH2B3, previously linked to CAD, blood pressure, TNF-α, cell counts and colorectal cancer." (PMID 29227965, 2017). "We included four studies to describe the association between the TNF-α T-857C polymorphism and colorectal cancer risk." (PMID 28115787, 2016). "And Wnt/β-catenin pathway can be activated by TNF-α in gastric tumor cells, colorectal cancer cells, as well as in a colitis-associated cancer mouse model." (PMID 26910375, 2016). "In this study, we investigated the role of this functional TNF-α-308G/A SNP in the promoter region of TNF-α gene as a potential colorectal cancer risk factor in a case–control study design with 142 case subjects and 184 control subjects." (PMID 27331018, 2016). "Tumor necrosis factor-alpha (TNF-α) contributes in inflammation and has been implicated in the development of colorectal cancer (CRC)." (PMID 26572151, 2016). "The literature evidence regarding the association of circulating concentrations of inflammatory biomarkers, other than CRP, IL-6, and TNF-α, and the risk of colorectal cancer is very sparse." (PMID 26321888, 2015). "A recent study with a mouse model showed that TNF-α is also produced in excess in early colonic lesions in cases of colorectal cancer, and the data supported the closest association between TNF-α and early tumor progression." (PMID 26719751, 2015). "Strictly, we can only conclude that TNF-a 308A was moderately associated with an increased risk of colorectal cancer in Western populations." (PMID 24404201, 2014). "For publication bias investigation, Begg’s funnel plot and Egger’s weighted regression were performed for the association between TNF-a polymorphisms and colorectal cancer." (PMID 24404201, 2014). "In this article, 15 studies were identified to evaluate the relationship between TNF-a polymorphisms and risk of colorectal cancer, and a total number of 3372 cases and 4523 controls were included." (PMID 24404201, 2014). "In this study, a meta-analysis was performed to investigate the association between common polymorphisms of TNF-a promoter region and colorectal cancer susceptibility." (PMID 24404201, 2014). "Searching of several databases was performed for all publications on the association between TNF-a polymorphisms and colorectal cancer." (PMID 24404201, 2014). "According to our study, TNF-a 308A polymorphism was associated with an elevated risk of colorectal cancer under homozygote comparison." (PMID 24404201, 2014). "Up to now, among all publications, 4 studies investigated the association between TNF-a 238 polymorphism and risk of colorectal cancer, but yielded contradictory results." (PMID 24404201, 2014). "Studies suggesting that circulating levels of IL-6 and TNF-α are associated with colorectal cancer are fairly consistent." (PMID 24235998, 2013). "We report, that Smad4-reexpressing human colorectal cancer cells like adenoma cells respond to TNFα with a moderate increase of all three chains encoding laminin-332 and with synergistic induction in response to the combination of TGFβ and TNFα." (PMID 20307265, 2010). "Studies on a larger cohort of colorectal cancer cases and matched controls are necessary to clarify the relationship between the TNFα -1031T/T and NOD2 3020insC polymorphisms and CRC." (PMID 18433468, 2008). "Furthermore, a meta-analysis comparing open and laparoscopic colorectal cancer surgeries revealed a strong association between serum TNF-α levels and early postoperative fatigue." (PMID 40529134, 2025).
colorectal cancer (continued). "On the one hand, they can significantly inhibit NF-κ B/p65 signaling pathway activity, thereby down-regulating IL-6, TNF-α and IL-1β and up-regulating IL-10 in the serum of patients with colorectal cancer, which further reduces the inflammatory response associated with colorectal cancer." (PMID 40520902, 2025). "After chemotherapy, we found that the plasma level of TNFα was significantly upregulated in colorectal cancer and that the level of TNFα was markedly associated with survival outcome in The Cancer Genome Atlas (TCGA) colon adenocarcinoma database (n = 597, log-rank p = 0.0409)." (PMID 38195677, 2024). "Additionally, in colorectal cancer, glutamine supplementation has been associated with decreased tumor necrosis factor-α, a reduced risk of wound infections, and shorter hospital stays." (PMID 38276310, 2024). "TNF expression in colorectal cancers is mostly associated with better prognosis." (PMID 39427065, 2024). "It has been suggested that polymorphic gene variations in the TNF-α promoter region that include 308G/A and 238G/A, might possess the risk of different cancers including colorectal cancer by regulating TNF-α cytokine synthesis." (PMID 37232720, 2023). "In addition, berberine is another antioxidant that inhibits the development of colitis-associated colorectal cancer by interfering with TNFα and IL-6-induced inflammatory responses in colonic macrophages, thereby inhibiting EGFR/ERK signaling in tumor cells." (PMID 36670988, 2023). "Third, the mendelian randomization analysis studies the lifetime effect of anti-TNF on the risk of colorectal cancer, it might underestimate the real effect of anti-TNF drugs." (PMID 36618924, 2022). "Anti-tumor: overexpression in colorectal cancer cells causes TNFα-mediated apoptosis." (PMID 36686729, 2022). "However, the target population that should receive anti-TNF for reducing the risk of colorectal cancer, the selection of a specific drug, and the treatment dose should be further investigated." (PMID 36618924, 2022). "Numerous studies have examined the association between TNF, microbiota, and colorectal cancer." (PMID 36140470, 2022). "Evidence from previously published studies was inconsistent in whether anti-TNF drugs reduce the risk of colorectal cancer." (PMID 36618924, 2022). "TNF-238 polymorphisms were reported to play a protective role against cervical cancer and are associated with a reduced risk of developing Hodgkin lymphoma as well as cervical, gastric, renal and colorectal cancers, again suggesting an inverse association." (PMID 33985540, 2021). "The gut microbiota, which colonize the entire intestinal tract, especially the colon, are closely linked to colorectal cancer through an association with inflammatory mediators such as tumor necrosis factor, nuclear factor kappa B, interleukins, and interferons." (PMID 33578830, 2021). "In the supplementary analysis, using four SNPs, there was some evidence of inverse associations of genetically-predicted TNF levels with intracerebral haemorrhage (OR, 0.19; 95% CI, 0.04, 0.92), colorectal cancer (OR, 0.23; 95% CI, 0.09, 0.60), and ovarian cancer (OR, 0.23; 95% CI, 0.06, 0.91)." (PMID 32805626, 2020). "Several studies have demonstrated that blocking IL-1β or TNF-α or using IL-17-deficient mice markedly attenuates the colonic inflammation and development of colorectal cancer 42-44, indicating that these cytokines are the key factors responsible for the local inflammation." (PMID 32550901, 2020). "Previous studies of TNF levels in relation to risk of colorectal cancer are inconsistent." (PMID 32805626, 2020).
colorectal cancer (continued). "According to other reports, TNF-α -238 promoter polymorphism seems to be associated with attenuated susceptibility to various cancers, including gastric carcinoma, uterine cervical carcinoma, colorectal carcinoma, renal cell carcinoma and lung cancer." (PMID 32592356, 2020). "The aim of this study was to investigate whether Kanglaite could inhibit epithelial mesenchymal transition caused by tumor necrosis factor-alpha using four colorectal cancer cell lines, HCT106, HCT116, LoVo and CT26." (PMID 29467927, 2018). "Therefore, from the point of view of population genetics, the role of TNF-α -308 G>A polymorphism in colorectal cancer requires further study." (PMID 28575042, 2017). "Furthermore, TNF-α has been reported to increase the activity of Wnt/β-catenin pathway in gastric tumor cells, colorectal cancer cells and in a colitis-associated cancer mouse model." (PMID 26910375, 2016). "However, scarce epidemiological evidence exists about a potential association between pre-diagnostic TNF-α concentrations and risk of colorectal cancer." (PMID 26321888, 2015). "However, the association between TNF-a 308 polymorphism and colorectal cancer risk became less significant under heterozygote comparison." (PMID 24404201, 2014). "Overall, TNF-a 308A polymorphism showed a significant association with increased risk of colorectal cancer in worldwide populations under homozygote comparison [AA vs. GG, OR (95% CI) = 1.46 (1.07–1.97)] other than heterozygote comparison [AG vs. GG, OR (95% CI) = 1.05 (0.93–1.19)]." (PMID 24404201, 2014). "Considering the small sample size of both the two meta-analyses (1,708 and 1,742, respectively), whether TNF-a 308 polymorphism is associated with colorectal cancer remains inconclusive." (PMID 24404201, 2014). "Together, we concluded that TNF-a 308A polymorphism was a general risk factor of colorectal cancer." (PMID 24404201, 2014). "When stratified by ethnicity, for Western populations, a significant association between TNF-a 308 and colorectal cancer risk was observed under homozygote comparison [AA vs. GG, OR (95% CI) = 1.39 (1.01–1.91)], but not heterozygote comparison [AG vs. GG, OR (95% CI) = 1.04 (0.94–1.15)]." (PMID 24404201, 2014). "However, the number of current studies on TNF-a 238 polymorphism and risk of colorectal cancer is relatively small, thus investigations involving more cases are needed in the future." (PMID 24404201, 2014). "Thus, TNFα and IL-17 are frequently both present in acute and chronic inflammation, and both have been linked to colorectal cancer." (PMID 23866118, 2013). "However, epidemiological studies of the associations of IL-6 and TNF-α with risks of colorectal cancer or adenoma, precursor lesions of cancer, however, have been inconsistent." (PMID 24235998, 2013). "The increasing association of the TNFα -1031 T/T genotype with the age of diagnosis of colorectal cancer suggests that there is a link between age-related remodeling of the immune system which results in a greater predisposition to disease with aging in the presence of this polymorphism." (PMID 18433468, 2008). "Therefore, inhibition of IL-1β, IL-6, and TNF-α may help reduce inflammation associated with colorectal cancer, potentially slowing tumor growth, angiogenesis, and metastasis." (PMID 41463421, 2025). "Intranasal insulin may decrease the risk of POCD and inhibit the elevated serum IL-6, TNF-α, and S100β levels in elderly patients after laparoscopic radical resection of colorectal cancer, which proves that intranasal insulin may be a promising therapeutic option for POCD." (PMID 38915348, 2024). "The role of TNF-α in the development of cancer and the associated elevated miR-21 expression has prompted us to investigate potential mechanisms whereby these mediators influence the progression of the metastatic phenotype in colorectal cancer epithelial cells." (PMID 36765584, 2023).
colorectal cancer (continued). "Intestinal barrier dysfunction is characterized by increased intestinal permeability to lumen endotoxin, showing remarkable predisposition to immune enteropathy, and colorectal cancer tumor necrosis factor (TNF)-α is associated with this pathological process, while the mechanism remains unknown." (PMID 34483933, 2021). "Serum TNF-α might as well be a risk factor for colorectal cancer." (PMID 26881177, 2016). "As for colorectal cancer, previous meta-analysis found that while C-reactive protein and interleukin-6 may be associated with risk of colorectal cancer, the few studies on tumor necrosis factor-α and risk of colorectal cancer mainly found null results." (PMID 27608842, 2016). "However, recently no integrated analysis has been made to get a definitive conclusion of whether TNF-a 238G/A is associated with colorectal cancer." (PMID 24404201, 2014). "Survival was negatively correlated with PD-L1, TNF-α, IL-6, and IL-10 in colorectal cancer; 4-1BB, TGF-β1, IL-8, and IL-10 in gastric cancer; and TGF-β1, IL-6, and IL-10 in pancreatic cancer." (PMID 42193466, 2026). "Given the established role of TNF-α in promoting inflammatory responses and modulating apoptotic sensitivity in colorectal cancer, these results provide mechanistic insight into the reported chemopreventive effects of statins in this malignancy." (PMID 41596561, 2026). "Collectively, these findings demonstrate that both atorvastatin and rosuvastatin effectively suppress TNF-α expression at both protein and mRNA levels in LPS-stimulated colorectal cancer cells." (PMID 41596561, 2026). "Having established that atorvastatin and rosuvastatin suppress ERK1/2 activation in colorectal cancer cells, we next examined TNF-α as a functionally relevant downstream effector." (PMID 41596561, 2026). "The consequent attenuation of ERK signalling diminishes TNF-α secretion, thereby disrupting the autocrine and paracrine inflammatory loops that sustain colorectal cancer cell survival." (PMID 41596561, 2026). "A meta-analysis comparing open and laparoscopic colorectal cancer surgery revealed a linear correlation between inflammatory factors, such as interleukin-6(IL-6), IL-1β, tumor necrosis factor-α (TNF-α) levels, neopterin immune index, and POFS." (PMID 40529134, 2025). "Lipopolysaccharide has been shown to increase the PKM2 expression and STAT3 promoter binding, leading to TNF-α and IL-1β production in colorectal cancer." (PMID 40982322, 2025). "Wei et al17 found a similar increase in blood levels of TNF-α, IL-1β, and IL-6 in a rat model of colorectal cancer." (PMID 40241344, 2025). "Inflammatory biomarkers, including CRP, IL-6, TNF - α and its receptors, adiponectin and leptin, play complex roles in colorectal cancer development." (PMID 39980561, 2025). "For instance, colorectal cancer patients with elevated serum TNF-α had a dramatically shorter median survival (~7.8 months) compared to those with low TNF-α (~38.4 months)." (PMID 40299527, 2025). "One patient with thyroid cancer and another with early-stage colorectal cancer resumed TNF inhibitor therapy after surgical resection due to persistent pain and uncontrolled disease activity; both remained recurrence-free during ≥5 years of follow-up." (PMID 41302997, 2025). "The top thirty most significant pathways highlighted several UC-relevant mechanisms, such as the IL-17 signaling pathway, Toll-like receptor pathway, TNF signaling pathway, apoptosis, and colorectal cancer pathway." (PMID 41465478, 2025). "IL-6, IL-1β, IL-10, IL-17, and TNF-α were selected as key mediators of inflammation and immune regulation in colorectal cancer." (PMID 41267807, 2025). "On the other hand, LPS induces pro-inflammatory cytokines (such as IL-1β, IL-6, and TNF-α) in a HMGB1-dependent manner to improve colorectal cancer progression." (PMID 40495163, 2025).
colorectal cancer (continued). "Activated immune cells produce chemokines and pro-inflammatory cytokines such as IL-1β and TNF-α, further exacerbating the injury of the intestinal epithelial barrier and leading to the occurrence of UC, and even the transition to colorectal cancer." (PMID 40904624, 2025). "Anthocyanins, particularly cyanidin‐3‐O‐glucoside, suppress inflammation and production of pro‐inflammatory cytokines (COX‐2, TNF‐α, and IL‐6) in colorectal cancer and hepatocellular carcinoma." (PMID 40321606, 2025). "A recent study evaluating the effect of TNFα on HT-29 colorectal cancer cells observed that TNFα secreted high levels of pro-tumorigenic cytokines IL-8 and IL-6, that aided tumor progression." (PMID 40558596, 2025). "Future efforts will focus on translating OC’s PAR-2 modulation for chondrosarcoma and its PAR-2/TNF-α/calcium signaling effects for colorectal cancer, both involving detailed mechanistic studies and nanotherapeutic delivery." (PMID 40564985, 2025). "For example, its overexpression correlates with poor prognosis in lung adenocarcinoma and promotes tumor invasion in colorectal cancer by activating the TNF-α/NF-κB pathway." (PMID 41595468, 2025). "Among these, the most relevant to UC pathogenesis included the IL-17 signaling pathway, Toll-like receptor signaling, TNF signaling, apoptotic pathways, and colorectal cancer-related mechanisms." (PMID 41465478, 2025). "Inflammation-related plasma proteins such as C-reactive protein (CRP), IL-6 (interleukin-6), TNF-alpha (tumor necrosis factor) and its receptors, adiponectin play complex roles in colorectal cancer development." (PMID 41464635, 2025). "This study investigates the association between Fusobacterium nucleatum presence and the expression of inflammation-related genes (IL6, IL1B, IL10, IL17, TNF) in tumor and matched normal tissues from Kazakhstani patients with colorectal cancer." (PMID 41267807, 2025). "The TNFα that is present in the tumor microenvironment (TME) has the potential to activate cell death pathways in colorectal cancer cells." (PMID 38195677, 2024). "It was found that Th17-type cytokines, IL-6 and TNF-α synergistically activate STAT3 to promote the growth of colorectal cancer cells." (PMID 38710698, 2024). "Blocking TNF can attenuate colorectal cancer by altering the composition and activity of the microbiota." (PMID 38717677, 2024). "In a TNF-α-stimulated tumour cell in the inflammatory colorectal cancer microenvironment, upon binding of TNF-α to its receptor TNFR1, adaptor proteins TRADD and TRAF2 are recruited with cIAP-1 and/or cIAP-2 and RIP kinase." (PMID 38600086, 2024). "Taken together, our results indicated that chemotherapy sensitizes colorectal cancer to release ATP via the caspase-8/3-mediated cleavage of PANX1 downstream of TNFα." (PMID 38195677, 2024). "In the present study, we found that TNFα promoted PANX1 cleavage through TNFR1 in a caspase 3-dependent manner in colorectal cancer." (PMID 38195677, 2024). "Here, we revealed that a high level of TNF-α in the colorectal cancer (CRC) microenvironment upregulated CCR8 expression in Tregs via the TNFR2/NF-κB signalling pathway and the FOXP3 transcription factor." (PMID 37935468, 2024). "Here, we demonstrated that TNFα-mediated PANX1 cleavage was essential for ATP release in response to chemotherapy in colorectal cancer (CRC)." (PMID 38195677, 2024). "The treatment also implicates 108 pathways, including apoptosis, TNF signaling pathway, apoptosis—multiple species, necroptosis, colorectal cancer, and other signaling pathways." (PMID 38148335, 2024). "Tumor necrosis factor (TNF)-mediated cell death can enhance chemotherapeutic drug-induced cell death in colorectal cancer." (PMID 38195677, 2024). "Here, we show that TNFα sensitizes colorectal cancer promote the release of ATP by caspase-8/3-mediated PANX1 cleavage via TNFR1 during chemotherapy-induced cell death." (PMID 38195677, 2024).